MIR7976 (microRNA 7976)
Synonyms: hsa-mir-7976
Gene: MicroRNA gene on chromosome 3 (127,587,111 to 127,587,176, reverse strand). Ensembl gene ENSG00000276083.
Homologues: Orthologues: chimpanzee MIR7976 (100% identical).